CASP1 (caspase 1)
Diseases named in the same sentence as CASP1 in open-access papers (continued):
Sharing a sentence is not in itself a finding about the gene and the disease.
autoimmune disease (23 papers, 2013 to 2025). A disorder resulting from loss of function or tissue destruction of an organ or multiple organs, arising from humoral or cellular immune responses of the individual to their own tissue constituents. "Classically, the NLRC4 is involved in the immune response against pathogens and autoimmune diseases and is part of the inflammasome complex that directly activates caspase-1." (PMID 40332346, 2025). "The specific ICE/caspase-1 inhibitor VX-765 is a pro-drug with improved oral bioavailability developed for the treatment of inflammatory and autoimmune diseases." (PMID 36200259, 2023). "The selective inhibitors of GSDMD, inflammasomes, and caspase-1 are identified to ameliorate inflammation and thrombosis, and some of them exhibit excellent therapeutic efficacy in several autoimmune diseases." (PMID 37063905, 2023). "IL-33/ST2 signaling has been found to upregulate CD11b, TLR4, caspase-1, and IL-1β in a number of human and animal studies of infection and autoimmune disease." (PMID 36741845, 2022). "Our results suggest that Gm614 protects GC B cells from death by suppressing caspase-1 transcription in autoimmune diseases." (PMID 33193409, 2020). "Hence, BNP could be further investigated also for its potential therapeutic effect on NALP3/ASC/Caspase-1 associated disorders also in consideration of the fact that many of the autoimmune diseases are refractory to most therapies and that immunosuppressive agents have many side effects." (PMID 28331244, 2017). "Our results suggest that caspase-1 inhibitor ameliorates experimental autoimmune myasthenia gravis by innate DC IL-1-IL-17 pathway and provides new evidence that caspase-1 is an important drug target in the treatment of MG and other autoimmune diseases." (PMID 26071315, 2015). "A study found that rapamycin decreased macrophage secretion of IL-18 and IL-1β by reducing caspase-1 activation, indicating that inhibition of mTOR may be advantageous for patients with inherited autoimmune diseases." (PMID 36595872, 2022). "The inflammasome NLRP3 is a multiprotein complex that regulates caspase-1 activation and assists in releasing proinflammatory cytokine IL1β, one of the most characterized cytokines known to play an important role in autoimmune diseases." (PMID 35035661, 2022). "Thirdly, pyroptosis mediated by activated caspase-1 promotes development of autoimmune diseases." (PMID 34707607, 2021). "Importantly, our results suggest that Gm614 protects GC B cells from death by suppressing caspase-1 transcription in autoimmune diseases." (PMID 33193409, 2020). "Thus, Gm614-mediated suppression of caspase-1 expression is at least partly involved in the imbalance between B-cell proliferation and death in autoimmune diseases." (PMID 33193409, 2020). "We hypothesized that if caspase-1 trafficking plays a role in metabolic and autoimmune diseases, the expression and the subcellular localization of caspase-1 substrates may be altered due to changes in the caspase-1 activity." (PMID 27842563, 2016). "Cysteinyl aspartate-specific proteinase-1 (caspase-1) inhibitor may be an important drug target for autoimmune diseases." (PMID 26071315, 2015). "Furthermore, we had previously shown that IL-1β, induced via caspase-1 and Nlrp3, plays a critical role in IL-17-mediated pathology in autoimmune disease." (PMID 23592988, 2013). "In addition, increased caspase-1 activation and IL-1β production by the constitutively active autoimmune disease-associated variants of NLRP3 were also linked to autoimmune diseases, indicating a crucial need for appropriate NLRP3 activation and IL-1β production." (PMID 35246034, 2022). "Collectively, the effect of NLRP3 inflammasome in autoimmune diseases involves the following two aspects: due to caspase-1 being the effector of inflammasome structure, IL-1β, IL-18, and pyroptosis modulated by activated caspase-1 play a major role in autoimmune diseases." (PMID 34707607, 2021).
autoimmune disease (continued). "We addressed the hypothesis that caspase-1 may be an important drug target for autoimmune diseases." (PMID 26071315, 2015). "NLRP3/caspase-1-dependent IL-1β/IL-18 release or NLRP3/caspase-1-dependent/GSDMD-mediated pyroptosis is crucial in inflammatory disease, autoimmune diseases, tissue injuries and other diseases." (PMID 38957662, 2024). "To date, NLRP3 inflammasome research has focused on the pathogenesis of a number of complex conditions, notably autoinflammation and autoimmune disease, that can be treated with the NLRP3-inhibitor MCC950 or the caspase-1 inhibitor Ac-YVAD-CMK." (PMID 30276509, 2019). "Recent studies have shown that pyroptosis is a characteristic of autoinflammatory and autoimmune diseases; We found pyroptotic phenomena reflected as high expression of NLRP3, caspase-1, GSDMD, and IL-1β in endometrial cancer lesions as identified by IHC analyses." (PMID 31924176, 2020).
pancreatic cancer (22 papers, 2017 to 2025). "Type II IFN (IFNγ) treatment can cause cell cycle arrest and inhibit the growth of pancreatic cancer cells by triggering caspase-1- and IRF1-dependent apoptosis." (PMID 35140750, 2022). "In summary, RP-6306 not only facilitates GSDMD cleavage but also robustly activates a network of upstream signaling pathways including NLRP3, AIM2, and Caspase-1 in pancreatic cancer cells." (PMID 40664640, 2025). "These AV-EVLPs can inhibit pancreatic cancer progression by increasing mitochondrial ROS release through the activation of caspase-1/3/7/9 and GSDMD/E-mediated pyroptosis in Panc-1 cells." (PMID 40604924, 2025). "Obesity, a significant risk factor for pancreatic cancer, induces macrophage pyroptosis through saturated fatty acids mediated by FABP4 in a caspase-1/ GSDMD-dependent manner." (PMID 39994107, 2025). "LCL161 18 is a pyrrolidine-thiazole-containing compound that triggers pyroptosis in pancreatic cancer, leukemia, and multiple myeloma cells by activating caspase-1 and GSDMD." (PMID 39316325, 2025). "AV-EVLP significantly inhibit pancreatic cancer progression by triggering mitochondrial ROS release through the activation of caspase-1/3/7/9-GSDMD/E-mediated pyroptosis." (PMID 40604924, 2025). "According to this study, PRGs risk models were defined with the combination of immune and signaling pathways genes (CASP4, GSDMC, NLRP1, PLCG1, IL-18, CASP1, and NLRP2), among which CASP4, NLRP1, PLCG1, IL-18, and CASP1 are overexpressed in pancreatic cancers." (PMID 37893166, 2023). "CASP1-dependent pyroptosis promotes the growth of pancreatic cancer cells when induced by macrophage stimulator factors." (PMID 38022537, 2023). "According to a previous report, CASP1 is related to comparatively lower survival of pancreatic cancer patients." (PMID 35433410, 2022). "Although it has been assumed that caspase-1 does not cause apoptosis, recent reports have suggested that, in human pancreatic cancer cells, caspase-1 plays an important role in cell death by inducing interferon gamma." (PMID 35719997, 2022). "According to a previous study, LPS-induced inflammation in the presence of ATP activates NLRP3, which enhances pancreatic cancer cell proliferation by boosting caspase-1 activity, resulting in total IL-1β production." (PMID 35677632, 2022). "We next enriched these 18 PRGs into pyroptosis signaling pathways and discovered that caspase-1, 3, and 8-dependent pyroptosis, as well as gasdmin B-mediated pyroptosis, were all closely related with pancreatic cancer." (PMID 36118860, 2022). "Excitingly, we found a recent report that more completely elaborates the role of NLRP3, CASP1, and IL-β in pancreatic cancer." (PMID 35677632, 2022). "CNV-positive cells expressed Krt20, a marker of pancreatic cancer cells, and Aim2, which activates caspase 1 to process Il1 and Il18 precursors and regulates inflammasome activation." (PMID 32908137, 2020). "Results showed that P2X7R's key inflammasome components, IL-1β and caspase-1 are highly expressed (p < 0.05) in pancreatic tumors." (PMID 29228654, 2017). "The enrichment of CASP1 in macrophages suggested a significant inflammatory response within the pancreatic cancer microenvironment, which may drive local immunosuppression and tumor progression." (PMID 40535567, 2025). "By contrast, the inhibition of caspase-1 by Ac-YVAD-CHO led to apoptosis in pancreatic carcinoma cells, implying that the role of caspase-1 in the survival and growth of cancer cells is also depending on the experimental condition, particularly determined by cancer cell types." (PMID 32155890, 2020). "Thus, it would be of interest to examine the expression and function of CYP1B1 in pancreatic cancer and determine its relationship with CASP1." (PMID 28388569, 2017). "In contrast to previous findings, CASP1 has an anti-apoptotic effect in pancreatic carcinoma." (PMID 28388569, 2017).
pancreatic cancer (continued). "Finally, to evaluate the risk and prognosis in pancreatic cancer more conveniently using pyroptosis-related genes, we constructed a prognostic model consisting of seven PRGs, including CASP4, GSDMC, NLRP1, PLCG1, IL-18, CASP1 and NLRP2." (PMID 35712482, 2022). "This leads to a significant increase in ROS, activation of caspase-1 and GSDMD, and ultimately induces pyroptosis in pancreatic cancer cells." (PMID 39994107, 2025). "These composites inhibited glucose and glutamine uptake of pancreatic cancer cells through the released BAY-876 and V-9302, leading to nutrition deprivation and oxidative stress, activating caspase 1 and GSDMD, and finally, inducing pyroptosis." (PMID 40375976, 2025). "Curcumin effectively attenuated the inflammatory microenvironment of pancreatic cancer by modulating a complex signaling network that downregulates NLRP3, CASP1 and CSF2 while simultaneously regulating expression of key pro-inflammatory factors within interleukin family." (PMID 40535567, 2025). "In this context, the increased production of ROS in pancreatic cancer cells exposed to 56 μg/mL of DIO-NPs correlated well with depletion of GSH content, increased levels of MDA, leakage of LDH outside the cells, and elevation of caspase-1 activity." (PMID 36834718, 2023). "Our results show that P2X7R (~20-fold), its key inflammasome components: caspase-1 (15-fold), IL-1β (~45-fold), and in addition to (data not shown) IL-18 (~35-fold), IL-33 (~93 folds), TNF-α (~13-fold) and COX-2 (~41-fold) are increased in pancreatic tumors compared to normal pancreas." (PMID 29228654, 2017).
renal fibrosis (22 papers, 2014 to 2026). A final common manifestation of a wide variety of chronic kidney diseases characterized by glomerulosclerosis and tubulointerstitial fibrosis. "Many studies have shown that elevated levels of NLRP3 and caspase-1 are associated with renal fibrosis in CKD patients, indicating that the NLRP3 inflammasome may participate in renal fibrosis." (PMID 36928344, 2023). "Caspase-11 was found to directly interact with caspase-1 in TECs, leading to maturation of IL-1β and renal fibrosis in unilateral ureteral obstruction mice." (PMID 37554279, 2023). "Caspase-1-mediated pyroptosis promotes the pathological processes of renal fibrosis in animal models, motivating the development of caspase-1 inhibitors as therapeutic medicines." (PMID 37500614, 2023). "The activation of the NLRP3 inflammasome promotes the activation of inflammatory caspases (caspase-1)-dependent pro-inflammatory hormones IL-1β and IL-18, which, in turn, promotes renal fibrosis." (PMID 36421424, 2022). "A recent study also found that caspase-11 stimulates the maturation of IL-1 to promote renal fibrosis by activating caspase-1." (PMID 32039201, 2019). "Taken together, these findings suggested an important role for canonical NLRP3 inflammasome activation (the NLRP3 inflammasome-caspase 1-IL-1β/IL-18 axis) in renal fibrosis in the murine UUO model of CKD." (PMID 28348462, 2017). "We demonstrated that TFNAs@PLT could reduce inflammation-mediated pyroptosis and apoptosis via Caspase-3/GSDME and NLRP3-mediated Caspase-1/IL-1β pathways in AKI, while also alleviating renal fibrosis through NLRP3/Caspase-1 and TNF-α/NF-κB pathways in CKD." (PMID 41355960, 2026). "Therefore, in light of their remarkable efficacy in animal models, future clinical trials with caspase-1 inhibitors are urgently needed to evaluate their efficacy in treating human renal fibrosis." (PMID 37500614, 2023). "Previous studies have shown that high glucose level significantly induces the expression of pyroptosis markers, including NLRP3, caspase-1, pro-caspase-1, IL-1β, and pro-IL-1β, in GMCs, whereas inhibiting NLRP3 with MCC950 suppresses NLRP3/caspase-1/IL-1β activation and decreases renal fibrosis." (PMID 36204129, 2022). "The NLPR3 inflammasome and caspase 1 substrate IL18 have been found to mediate renal fibrosis." (PMID 33898439, 2021). "The typical NLRP3/ASC/caspase-1/IL-1β/IL-18 axis promotes the pathophysiology of various kidney diseases by mediating inflammation, and this is likely a critical priming mechanism for renal fibrosis." (PMID 32039201, 2019). "In conclusion, caspase-1 activation may play an important role in the development of inflammation and pyroptotic cell death, which may result in hypertension and renal fibrosis in aldosterone-salt-treated rats." (PMID 24695748, 2014). "Furthermore, through the NLRP3/caspase-1/IL-1β pathway, IL-22 can reverse the overexpression of fibronectin, collagen IV, and extracellular matrix in mouse renal glomerular mesangial cells, thereby ameliorating renal fibrosis and proteinuria excretion in DN." (PMID 36776877, 2023). "This study identifies host cysteine proteases—particularly cathepsin L and caspase-1—as unrecognized drivers of CAUTI pathogenesis and renal fibrosis." (PMID 40980878, 2025). "Owing to modulation of the GPx-1/NLRP3/Caspase-1 pathway, Se@BSA NPs ameliorated the renal function of IRI-AKI mice in a dose-dependent manner and dramatically arrested the development of renal fibrosis after AKI." (PMID 35664065, 2022). "During acute kidney injury (AKI) and renal fibrosis induced by nondiabetic renal disease, the mechanism of pyroptosis involves classical pyroptosis in the caspase-1/GSDMD pathway as well as nonclassical pyroptosis in the caspase-4/5/11 pathway." (PMID 39000237, 2024).
renal fibrosis (continued). "In patients with renal fibrosis, the expression levels of NLRP3 and Caspase-1 are significantly up-regulated, suggesting that the NLRP3 inflammasome may be activated and involved in regulating renal fibrosis." (PMID 38820434, 2024). "NLRP3 is associated with renal fibrosis after UUO, whereas IL-1β, IL-18, and caspase-1 are not necessary for these pathways." (PMID 37685978, 2023). "Increasing evidence strongly indicates that the expression levels of NLRP3 and caspase-1 are significantly elevated in the kidneys of CKD or fibrosis patients, suggesting that the NLRP3 inflammasome may be activated and involved in the regulation of renal fibrosis." (PMID 32039201, 2019).
acute kidney injury (21 papers, 2009 to 2026). Sudden and sustained deterioration of the kidney function characterized by decreased glomerular filtration rate, increased serum creatinine or oliguria. "Collectively, these results suggest that caspase-1 is a critical pathogenic factor leading to the development of acute kidney injury and its pharmacological inhibition has a preventive effect against cisplatin-induced nephrotoxicity." (PMID 30670928, 2018). "Additionally, overactivation of caspase-1 has been associated with myocardial infarction, ischemic brain injury, chronic colitis, and acute renal failure." (PMID 36189207, 2022). "VD/VDR signaling down-regulated the expression of pyroptosis associated markers NLRP3, GSDMD-N, Cleaved Caspase-1 and mature IL-1βin AKI models, and partially alleviated cisplatin induced acute kidney injury by inhibiting pyroptosis mediated by NF-κB." (PMID 37483634, 2023). "Ac-YVAD-cmk, a specific and irreversible caspase 1 inhibitor, has demonstrated effectiveness in acute kidney injury (AKI) models in rodents." (PMID 38740765, 2024). "Knockouts of caspase-1 or NLRP3 result in the attenuation of acute kidney injury induced by ischemia-reperfusion injury." (PMID 38740765, 2024). "It has been shown that the interaction between C/EBPβ and TFAM activates NLRP3/caspase-1 and promotes the development of acute kidney injury." (PMID 37624173, 2023). "Retrospective multicentre cohort studies have shown that minocycline inhibits caspase-1 to reduce the incidence of acute renal failure." (PMID 36532040, 2022). "AKI is previously known as acute kidney failure, and the study found that repurified LPS can activate the caspase-1/IL-1β pathway during acute kidney failure, leading to pyroptosis." (PMID 34007404, 2021). "In recent years, it has been intensively reported that NLRP3 inflammasome/Caspase-1/IL-1β signaling pathway was involved in renal tubular lesion during acute kidney injury." (PMID 31616439, 2019). "In another study of I/R-induced ARF, it was concluded that acute kidney injury causes the NLRP3 inflammasome to be released by directly affecting the renal tubular epithelium, which leads to the activation of caspase-1, causing inflammatory cell infiltration and the activation of cytokines." (PMID 34135984, 2021). "MIN inhibits caspase 1, caspase 3, and inducible nitric oxide synthase, leading to the hypothesis that coadministration of CST with MIN (CST-MIN) may reduce the incidence of acute renal failure as well as produce additive or synergistic antimicrobial effects." (PMID 29038261, 2018).